TRPM2 (transient receptor potential cation channel subfamily M member 2)
Diseases named in the same sentence as TRPM2 in open-access papers (continued):
Sharing a sentence is not in itself a finding about the gene and the disease.
diabetes (continued). "In current study, we focused on TRPM2 ion channel, and revealed that diabetes triggers TRPM2 over-expression and activates TRPM2 ion channel, which will induce excessive apoptosis of ECs and aggravate BSCB destruction." (PMID 37215981, 2023). "This explains that diabetes alone also promotes oxidative stress, TRPM2 over-expression and ECs apoptosis in spinal cord tissue." (PMID 37215981, 2023). "We have analyzed the differential expressed genes and found that comparing with SCI group, the mRNA level of Trpm2 is significantly elevated in spinal cord from diabetes combined with SCI rat." (PMID 37215981, 2023). "In this study, we observed that diabetes significantly enhances the expression of TRPM2 in ECs after SCI." (PMID 37215981, 2023). "Our mechanistic studies showed that diabetes significantly induces elevated ROS level to activate TRPM2 ion channel of ECs." (PMID 37215981, 2023). "It was observed that TRPM2 inhibitor (2-APB) treatment significantly suppresses ROS level in spinal cord from diabetes combined with SCI rat." (PMID 37215981, 2023). "For example, increased oxidative stress promotes overactivation of TRPM2 channel in diabetes and obesity." (PMID 33716794, 2021). "Both of these studies indicated that increased oxidative stress, present in diabetes and obesity, are modulating the TRPM2 channel, leading to elevated channel activity." (PMID 33716794, 2021). "In particular, IF staining showed that the fluorescence intensity of TRPM2 staining was markedly increased in the epithelial tubular cells of kidneys of mice with HFD/STZ-induced diabetes." (PMID 34845114, 2021). "Recently, pharmacological inhibition of TRPM2 channels was shown to obviously attenuate cognitive deficits in rodent models of diabetes, global ischemia, chronic cerebral hypoperfusion, aging, epilepsy and AD." (PMID 34720898, 2021). "Interestingly, TRPM2 expression level was correlated with damage and ROS levels in sciatic nerves in diabetic neuropathic pain, suggesting a role for TRPM2 in diabetic neuropathy." (PMID 41511359, 2026). "However, through the blockage of the TRPM2 in the neurons of laboratory animals with diabetes mellitus, antioxidant therapies, such as the RESV, decreased the amount of [Ca2+]i and oxidants." (PMID 38976129, 2024). "The roles of TRPM2 in diabetes or β-cell function have been studied." (PMID 38953285, 2024). "Current research findings suggest that TRPM2 activation could be a significant factor in the onset and progression of neurodegenerative diseases or diabetes." (PMID 39007141, 2024). "Given TRPM2’s role in both atherosclerosis and GLP-1-induced insulin secretion further research on GLP-1/TRPM2 interactions could enable further pharmacological targeting of macrophage-related inflammation in diabetes and ASCVD." (PMID 39200816, 2024). "Therefore, we have focused on the effect of TRPM2 ion channels on BSCB in diabetes mellitus with SCI." (PMID 37215981, 2023). "More importantly, we found that after SCI, excessive ROS may be an important mechanism for diabetes promoting the over-expression of TRPM2 on ECs." (PMID 37215981, 2023). "However, most studies consider TRPM2 a potential therapeutic target for antagonizing oxidative stress-related pathological conditions such as diabetes, inflammation, neurodegeneration, cardiovascular disease, and stroke." (PMID 36810113, 2023). "Thus, a further investigate into the effect of neuron-derived TRPM2 protein on diabetes combined with SCI recovery is needed." (PMID 37215981, 2023). "It was showed that TRPM2 inhibition alleviates the adverse effect of diabetes on apoptosis and angiogenesis in ECs of spinal cord, consequently promotes the locomotor function recovery of diabetes combined with SCI rat." (PMID 37215981, 2023).
diabetes (continued). "Furthermore, we had detected the expression level of TRPM2 protein in spinal cord and found that TRPM2 is up-regulated due to diabetes or SCI, more importantly, it was significantly up-regulated under diabetes combined with SCI condition." (PMID 37215981, 2023). "Therefore, the regulatory effect of diabetes on other ion channels and the relationship between TRPM2 channel and other ion channels are need to be further explored in future." (PMID 37215981, 2023). "Therefore, our study shows that NAC regulates TRPM2 activation in the testicular tissue of patients with diabetes and has tissue-protective properties." (PMID 37288204, 2023). "It has also been observed that NAC regulates TRPM2 activation in the early stages of diabetes." (PMID 37288204, 2023). "TRPM2 knockdown by AAV2-shTRPM2 neither changed the levels of FBG nor the weight loss in mice with HFD/STZ-induced diabetes." (PMID 34845114, 2021). "Here, our findings showed that TRPM2 might activate TGF-β1 to aggravate the development of kidney fibrosis in mice with HFD/STZ-induced diabetes." (PMID 34845114, 2021). "NAC exerted protective actions on DRG TRPM2 currents induced by diabetes in brain oxidative damage." (PMID 30551603, 2018). "More importantly, many studies show that TRPM2 channel mediates ROS-induced cell death through permeating excessive calcium into cells, which results in many kinds of diseases including ischemia injury, diabetes and inflammatory diseases." (PMID 29915540, 2018). "Involvement of TRPM2 in type 1 and type 2 diabetes mellitus has been suggested and the current hypotheses, including impairment in insulin secretion due to dysfunction of TRPM2, have been discussed in detail previously." (PMID 27548188, 2016). "Furthermore, since TRPM2 can be activated by oxidative stress, it has recently been seen as a potential therapeutic target against oxidative stress-related diseases, including diabetes, inflammation, myocardial infarction, and neurodegenerative diseases." (PMID 37288204, 2023). "Thus, we have targeted the TRPM2 role on diabetes exacerbating the BSCB destruction." (PMID 37215981, 2023). "Taken together, the current knowledge of TRPM2 has provided the basis for the development of pharmacologic inhibitors of TRPM2 in order to treat debilitating conditions that involve excessive cell death, including stroke, diabetes, immune disorders and inflammation." (PMID 25760245, 2015). "Our study has focused on transient receptor potential melastatin 2 (TRPM2) channel and investigated its regulatory role on integrity and function of BSCB in diabetes combined with SCI rat." (PMID 37215981, 2023). "Taken together, TRPM2 inhibition partially restores BSCB integrity in spinal cord from diabetes combined with SCI rat, indicated that TRPM2 is the key target for diabetes exacerbating BSCB destruction." (PMID 37215981, 2023). "Therefore, TRPM2 is closely related to many human diseases, such as myocardial infarction, ischemic stroke, Alzheimer’s disease, cardiomyopathy, atrial fibrillation, hypertension, atherosclerosis, inflammatory lung injury, diabetes, ischemic kidney disease, and many cancers." (PMID 35159300, 2022). "In conclusion, we showed that TRPM2 silencing significantly ameliorated fibrosis and inflammation in the kidneys of mice with HFD/STZ-induced diabetes, and this effect was largely achieved by the inhibition of TGF-β1-activated JNK1 activation." (PMID 34845114, 2021). "As an oxidative stress sensor, transient receptor potential melastatin 2 (TRPM2) channel is involved in many physiological and pathological processes including warmth sensing, ischemia injury, inflammatory diseases and diabetes." (PMID 29915540, 2018). "For example, studies on pancreatic β-cells (diabetes model) and neuronal cells (PD model) concurrently examined roles for NOX2, TRPM2, Ca2+, Zn2+, and Complex III (in PD model only) in lysosomal/mitochondrial damage and ROS amplification, demonstrating the circuit’s role in cell death." (PMID 40722879, 2025).
diabetes (continued). "Compared to control group, the protein expression of TRPM2, bax, cleaved caspase-3, and P62 was significantly elevated, and the protein expression of bcl-2 and LC3-II was significantly decreased in the myocardial tissues of the HFD/STZ-induced diabetes group." (PMID 38308007, 2024). "Because oxidative stress leads to TRPM2-mediated cell death, in noncancerous cells TRPM2 is a therapeutic target in conditions such as inflammation, stroke, and diabetes due to the protective effects elicited following TRPM2 antagonism." (PMID 37445615, 2023). "Inhibition of TRPM2 with 2-Aminoethyl diphenylborinate (2-APB) or TRPM2 siRNA will ameliorate the apoptosis of ECs and promote angiogenesis, subsequently enhance BSCB integrity and improve the locomotor function recovery of diabetes combined with SCI rat." (PMID 37215981, 2023). "Here, we discussed whether TRPM2 knockdown has a potential protective effect in the progression of renal inflammation and fibrosis in mice with HFD/STZ-induced diabetes." (PMID 34845114, 2021). "Therefore, inhibiting the expression of TRPM2 and NHE1 may become a new strategy for the treatment of ED induced by diabetes." (PMID 36421426, 2022). "Despite, we could not rule out the possibility that TRPM2-activated renal inflammation and fibrosis might be caused by the activation of p38 and ERK1/2 in mice with HFD/STZ-induced diabetes." (PMID 34845114, 2021). "In this study, we confirmed that diabetes is not conducive to the repair of BSCB destruction after SCI, and further revealed that diabetes will mediate Ca2+ influx by inducing the over-expression of TRPM2 in ECs and activating TRPM2 ion channel." (PMID 37215981, 2023).
ischemia (27 papers, 2014 to 2025). A hypoperfusion of the BLOOD through an organ or tissue caused by a PATHOLOGIC CONSTRICTION or obstruction of its BLOOD VESSELS, or an absence of BLOOD CIRCULATION. "Another study, by contrast, found that heart functions were improved in Trpm2 KO mice, suggesting that a deficiency in TRPM2 protects heart against ischemia-reperfusion injury." (PMID 27618067, 2016). "In the brain, TRPM2 expression is widespread in neurons throughout the hippocampus, cerebellum, and cortex and has been implicated in pathologies such as Alzheimer's disease, dementia, bipolar disorder, and ischemia." (PMID 34659399, 2021). "Transient receptor potential melastatin-related 2 (TRPM2) channel, a molecular sensor for reactive oxygen species (ROS), plays an important role in cognitive dysfunction associated with post-ischemia brain damage thought to result from ROS-induced TRPM2-dependent neuronal death during reperfusion." (PMID 29311807, 2017). "Thus, the TRPM2 loss appears to protect β-amyloid-induced or ischemia-induced neurotoxicity." (PMID 30215158, 2019). "Studies have demonstrated that TRPM2 contributes to neurodegeneration and inflammatory processes in Alzheimer's disease, ischemia, multiple sclerosis, and epilepsy, suggesting TRPM2 as a promising therapeutic target." (PMID 40665621, 2025). "Studies suggest that non-selective transient receptor potential melastatin 2 (TRPM2) channels contribute to brain injury in models of ischemia, however TRPM2 remains understudied following TBI." (PMID 40352737, 2025). "This study investigates CD38 as a potential regulator of TRPM2, highlighting a novel target to reverse hippocampal synaptic plasticity deficits after ischemia." (PMID 40822706, 2024). "TRPM2 is expressed in hippocampal, cortical, and microglial cells; however, the effect of TRPM2 on ischemia remains controversial." (PMID 36527242, 2023). "In tMCAO animal models, ROS overproduction predominates during the reperfusion process and can activate TRPM2 channels to exacerbate ischemia-reperfusion injury." (PMID 36921602, 2023). "Both wild-type (WT) and TRPM2–/– mice were subjected to 1 h of ischemia, and sacrificed after 3-, 6-, 12-, 24-, and 48-h reperfusion." (PMID 37275121, 2023). "Cardiac arrest/cardiopulmonary resuscitation (CA/CPR) in juvenile (p20-25) mice was used to investigate the role of ion TRPM2 channels in neuroprotection and ischemia-induced synaptic dysfunction in the developing brain." (PMID 34659399, 2021). "Further research is needed to clarify these somewhat contradictory roles of TRPM2 in the response of neuronal, kidney, and cardiac myocytes to ischemia–reperfusion." (PMID 34439491, 2021). "The blood flow in ischemic limbs in WT mice was recovered faster and better after 28 days post-ischemia than in chimeric TRPM2-KO mice, namely, TRPM2-KO mice with prior transplanted with bone marrow from WT mice to restore the TRPM2 expression in immune cells." (PMID 34063677, 2021). "A role for TRPM2 channels in mediating neuronal injury following ischemia has been proposed for several years." (PMID 34659399, 2021). "The study also investigated that ischemia-induced memory deficits were mediated by the aberrant activity of TRPM2-CaN-GSK3β signaling cascade that actively inhibits synaptic plasticity." (PMID 33455532, 2021). "The recovery of memory function with delayed tatM2NX administration is consistent with our electrophysiology data suggesting that delayed TRPM2 inhibition reverses ischemia-induced LTP impairments." (PMID 34659399, 2021). "The same study also examined the role of the TRPM2 channel in neovascularization in mice after introduction of hindlimb ischemia via femoral artery ligation." (PMID 34063677, 2021). "In vivo, FPP accumulates in MCAO model, and Simvastatin, Zoledronic acid, or TPPO treatment decreases the infarct volume in MCAO, suggesting the involvement of FPP and TRPM2 axis in the pathology of ischemia." (PMID 33901180, 2021).
ischemia (continued). "Previous studies verified that in a rodent disease model of ischemia, TRPM2 mRNA levels were significantly increased." (PMID 32825703, 2020). "Such information is helpful in gaining mechanistic insights into TRPM2-dependent delayed neuronal death responsible for ischemia-reperfusion brain damage." (PMID 30625984, 2019). "We recently show a critical role of TRPM2-dependent increase in the [Zn2+]c in post-ischemia hippocampal neuronal death." (PMID 29416015, 2018). "This experiment supports the pivotal role of TRPM2 expressed in bone marrow-derived immune cells in the pathomechanism of ischemia-reperfusion brain injury." (PMID 27618067, 2016). "Despite this data implicating TRPM2 as a promising candidate for neurorestorative therapy, the precise upstream mechanisms governing ongoing TRPM2 activation in both sexes after ischemia are largely unknown." (PMID 40822706, 2024). "In addition, pretreatment with antioxidants such as N-acetyl cysteine and thymoquinone inhibits the Ca2+ entry by reducing the TRPM2 gene expression in the hepatocyte model of ischemia-reperfusion injury." (PMID 39329114, 2024). "TRPM2 inhibition using our novel and selective peptide inhibitor tatM2NX acutely after reperfusion in adults resulted in male-specific neuroprotection following global and focal ischemia." (PMID 34659399, 2021). "It has been suggested that the release of Zn2+ from lysosomes via TRPM2 channels may play a role in the “delayed” neuronal cell death that follows ischemia and reperfusion in the brain, such as in stroke." (PMID 34439491, 2021). "Therefore, modulation of TRPM2 can be a potential therapeutic strategy to prevent ischemia-induced neuronal death." (PMID 33455532, 2021). "Therefore, modulation of the TRPM2 channel can be a potential therapeutic target to prevent ischemia-induced neuronal death." (PMID 32825703, 2020). "In addition, TRPM2 channels preserved mitochondrial biological function and further protected the hearts which suffered from ischemia-reperfusion injury." (PMID 29250536, 2017). "Furthermore, TRPM2-dependent neuronal death has been related to post-ischemia brain damage and Alzheimer’s disease." (PMID 29311807, 2017). "Following this logic, we hypothesized that if the TRPM2 level was increased by global cerebral ischemia-induced cell death cascades, regulation of TRPM2 as a potential target for preventing ischemia-induced injury could ameliorate a diverse number of cerebral pathologies associated with ischemia." (PMID 32825703, 2020). "Furthermore, activation of the TRPM2 channel increased Ca2+ influx, mitochondrial membrane depolarization‐induced free oxygen radicals, release of apoptotic factors (including caspases 3 and 9), and eventual cell death in ischemia‐induced hippocampal neuronal injury." (PMID 36527242, 2023). "Mounting evidence show that TRPM2 interacts with multiple regulatory pathways in neurons, glia, and cells of immune system and BBB, which leads to severe brain injury after ischemia." (PMID 33455532, 2021). "During a period of acute ischemia in vivo or oxygen-glucose deprivation (OGD) in vitro, TRPM2 is activated by cellular stress and contributes to ischemia-induced membrane depolarization, intracellular calcium accumulation, and cell swelling." (PMID 33455532, 2021). "Transient receptor potential melastatin 2 (TRPM2) channel is a Ca2+-permeable, redox-activated cardiac ion channel protective in ischemia–reperfusion, but whether it regulates atrial endocrine output under stress is unclear." (PMID 41511308, 2025). "Acute TRPM2 inhibition with tatM2NX protected hippocampal CA1 neurons in adult males only, consistent with data demonstrating male-specific neuroprotection in regard to TRPM2 channel inhibition or knockdown after adult ischemia." (PMID 34659399, 2021). "The developing brain responds differently to injury than the mature brain; however, TRPM2 channels have not been studied in the juvenile brain after ischemia." (PMID 34659399, 2021).
ischemia (continued). "A recent study using TRPM2-KO mice has also demonstrated an important role for the TRPM2 channel in mediating brain damage after transient ischemia, but not ischemia without reperfusion." (PMID 26300888, 2015). "Additional research has demonstrated that TRPM2, TRPM6, TRPM7, and TRPM8 may impact hepatic ischemia-reperfusion injury, with TRPM2 knockout exhibiting a reduction in such injury through the activation of autophagy and inhibition of autophagy-negative regulation of the NLRP3 inflammasome pathway." (PMID 38255767, 2024). "No details about the interaction of TRPM2 and astrocytes has been reported, but we assumed that there must be some ischemia-related cascades between TRPM2 channels and astrocytes, and began to test this hypothesis." (PMID 32825703, 2020). "It was speculated that TRPM2 expressed in neutrophils, rather than the heart, is important for ischemia-reperfusion heart injury." (PMID 27618067, 2016).